CRH (corticotropin releasing hormone)
Diseases named in the same sentence as CRH in open-access papers (continued):
Sharing a sentence is not in itself a finding about the gene and the disease.
Anxiety (continued). "Moreover, a population of CRH positive GABAergic long-range-projecting neurons in the extended amygdala innervates the ventral tegmental area, and the chronic lack of CRH from this type of neurons produces anxiety." (PMID 32802040, 2020). "Selective activation of hippocampal CRH neurons by Gq did not alter locomotor activity (3379 ± 220 basic movements) or anxiety-like behavior in the open field (10.9 ± 3.0% time in center) compared to vehicle-injected controls (3095 ± 25 basic movements; 9.3 ± 3.1% time in center)." (PMID 29346425, 2018). "Silencing CRH neurons using Gi did not significantly alter anxiety-like behavior in the open field (17.4 ± 2.0% time in center) or light-dark box (31.6 ± 2.8% time in light) compared to GFP-injected controls (13.2 ± 2.2% time in center; 22.0 ± 6.3% time in light)." (PMID 29346425, 2018). "Limbic regions are not the only modulators of CRH activity in anxiety behavior." (PMID 23077729, 2012). "Given that CeMCRH neurons play a critical role in the modulation of anxiety and that LPGiCA neurons are involved in regulating autonomic responses to various stressors, we chose to focus on exploring whether PRV-infected CeM and LPGi neurons express CRH and TH, respectively." (PMID 37847562, 2023). "EA and MB were able to regulate the concentration of CRH in serum and protein expression in the peripheral and central at different levels and promote the recovery of the HPA axis that may be the basis for EA and MB to improve colonic pathology and alleviate anxiety behavior in DSS-induced colitis." (PMID 30881446, 2019). "However, whether severe stress is able to switch CRH action from positive to negative in the context of anxiety, social and/or depression-like behavior, remains largely unexplored." (PMID 31619956, 2019). "Similarly, ablating CRH neurons with DTA did not impact anxiety-like behavior (DTA: 18.9 ± 1.7% time in center; Control: 18.9 ± 1.8% time in center), nor was locomotor activity in the open field test altered (DTA: 3441 ± 224 basic movements; Control: 3088 ± 161 basic movements)." (PMID 29346425, 2018). "The same result is for models with CRH over-expression antagonizable by CRHR1 antagonists, where some lines do exhibit higher anxiety and vulnerability to stress, but in other lines that do not exhibit these traits, a UCN1 downregulation was found." (PMID 36004833, 2022). "In contrast, the moderately CRH-positive PAG was shown to regulate restraint stress-induced anxiety-like behavior in Wistar rats, tested by nonselective CRH receptor antagonist (alpha-helical CRH9-41) microinjections." (PMID 34445795, 2021). "Deletion of CRHR1 in Mor-Ens alleviated anxiety, depression, and impaired social interaction, while it did not affect conditioned aversion during opiate withdrawal, suggesting that CeA GABAergic and CRH connections with Mor-Ens might exert not exactly the same effects on negative effect." (PMID 34642456, 2021). "The non-suppressor group, which showed higher anxiety, more severe depressive symptoms and a distinguished response in the DEX/CRH, should be regarded as one entity in terms of different biological and psychological reactions." (PMID 27582123, 2016). "In male rodents, the stimulation of these interneurons leads to the release of CRHBP and the reduction of CRH activity and anxiety, while in female rodents CRHBP was not able to effectively inhibit CRH activity, which may be due to higher levels of CRH in paraventricular nuclei (PVN)." (PMID 36004833, 2022). "However, it could be relevant to the evidences that CRHR1 exhibits higher affinity to CRH than CRHR2 and the lack of CRHR1 leads to a greater influence to anxiety." (PMID 30898126, 2019). "Our data show that in a non-Pavlovian anxiety-related setting, CRH-dependent modulation of BLA−CE connectivity was mediated by presynaptic effects (, 4c), which might, in part, synergize with CRH-driven postsynaptic facilitation of BLA inputs to CEl SOM+ cells." (PMID 29904149, 2020).
depression (294 papers, 2004 to 2026). "In depression, increased hypothalamic volume has been correlated with severity, while dysregulation of cortisol, corticotropin-releasing hormone (CRH), and oxytocin has been linked to generalized anxiety disorder." (PMID 39851502, 2025). "Depression is among the most common psychiatric conditions associated with AA, characterized by an excessive release of CRH." (PMID 38772922, 2024). "Depression, by stimulating the sympathetic system and increasing corticotropin-releasing hormone levels, can lead to increased heart rate, a known risk factor for cardiac events." (PMID 38541087, 2024). "Various endocrine factors, including CRH and glucocorticoids, have been implicated in the structural and intracellular abnormalities seen in depression." (PMID 38927393, 2024). "Chronic inflammation and depression emerged to be associated also with increased corticotropin-releasing hormone (CRH) and glucocorticoid receptor resistance." (PMID 38138916, 2023). "In people with depression or schizophrenia, the continuous effect of CRH on the HPA axis causes increased cortisol, ACTH, and decreased feedback, which results in pathological reactions in the body." (PMID 37998661, 2023). "Joined studies found that alterations in methylated levels of CRH were associated with post-traumatic stress disorder, bipolar disorder, suicide attempts, and major depressive disorder in HIV patients." (PMID 37190549, 2023). "Social stressors in rodents were shown to affect neurobiological mechanisms implicated in depression, including the activation of proinflammatory cytokines, increased levels of GCs, and upregulation of CRH and its receptors." (PMID 35682846, 2022). "It is proven that psychiatric disorders like stress or depression, through the transmission of nerve signals to the hypothalamus, cause the secretion of CRH, ACTH, and glucocorticoids." (PMID 36201406, 2022). "This goes in line with observed HPA axis dysfunction in patients with major depression or schizophrenia, where the continuous effect of CRH on the HPA axis causes disbalance (increased cortisol, increased ACTH, reduced feedback) and results in a pathology." (PMID 36004833, 2022). "Activation of caudal DR by inescapable shock stress or by CRH injection is associated with depression-like behavior providing stronger support for a pro-depression effect of caudal DR." (PMID 31114473, 2019). "CRH also increases microglial expression of IL-18 which is implicated in stress, depression, and PTSD conditions." (PMID 29302258, 2017). "In atypical depression, there is CRH deficiency with a down-regulation of the HPA axis with decreased cortisol secretion, and a decreased sympathetic activity." (PMID 28931368, 2017). "First, the association between the reaction in the DEX/CRH test and the severity of depression determined by the HAMD assessment was investigated." (PMID 27582123, 2016). "Activation of the CRH system is a hallmark of major depression with melancholic features associated with hypercortisolism." (PMID 25878903, 2015). "Increased responsiveness in the dexamethasone/CRH test has long been known to be a potent risk marker for depression." (PMID 24596569, 2014). "In the context of psychiatric disorders, CRH dysfunction is associated with the occurrence of post-traumatic stress disorder, major depression, anorexia nervosa, and anxiety disorders." (PMID 23077729, 2012). "For example, clinically, excessive production of vasopressin is known to cause SIADH, whereas excessive CRH causes Cushing disease, depression, and anorexia nervosa." (PMID 19787076, 2008). "On the other hand, the dys-regulation of CRH in these regions probably causes depression or mood disorders." (PMID 19787076, 2008). "Furthermore, hyperactivity of the HPA axis is a well-established neuroendocrine hallmark of depression, with elevated levels of CRH, ACTH, and CORT commonly observed in the cerebrospinal fluid of depressed patients." (PMID 40989841, 2025).
depression (continued). "As the CRH system plays a role in depression-stress response and CRH SNPs are depression risk variants, and as CRHR1 variants modulate antidepressant response, we hypothesize that CRH system resistance may lead to hypercortisolism." (PMID 38092990, 2025). "Depression has been linked to disturbances in corticotropin-releasing hormone (CRH) levels." (PMID 39085220, 2024). "A hereditary predisposition to dysfunction of the HPA axis could therefore induce CRH-noradrenergic system abnormalities, causally contributing to depression, T2D, and depression–T2D comorbidity." (PMID 38927393, 2024). "With increased HPA axis activity in depression, the hippocampus becomes sensitive to a constant, elevated level of corticoliberin, the corticotropin-releasing hormone (CRH), which in turn causes the body to release more cortisol in an attempt to regulate CRH production." (PMID 36768580, 2023). "Cytokine stimulation of the HPA axis may also be a factor in depression pathophysiology, as hypersecretion of CRH is associated with depression." (PMID 35054853, 2022). "Depression, stressful life events, food insecurity, and financial strain were associated with CRH in the direction hypothesized after adjustment, however the confidence intervals included the null value." (PMID 33824413, 2022). "Changes in ghrelin and corticotropin-releasing hormone, associated with increased gut motility, may change microbiome composition, in turn impacting inflammation and the development of depression." (PMID 33414380, 2021). "It has been suggested in previous studies that major depression in a susceptible host may lead to alterations in corticotropin-releasing hormone (CRH) levels which act at the placental interface propagating a cascade to preterm birth." (PMID 32977397, 2020). "Depression is, however, a heterogeneous disease where melancholic depression is accompanied by an activated CRH system, anxiety, loss of appetite, weight loss and insomnia, whereas atypical depression is accompanied by CRH deficiency, increased appetite, weight gain, lethargy, and hypersomnia." (PMID 30885233, 2019). "During the postpartum period, the normally elevated CRH occurring during late pregnancy, may down-regulate hypothalamic CRH and cortisol output and increase the risk for depression." (PMID 26322643, 2015). "Despite the lack of compelling enrichment in depression-linked genes, MSET identified corticotropin releasing hormone (CRH) binding protein (Crhbp) as the lone gene dynamically regulated in maternal mPFC that appeared in all depression databases utilized in this study." (PMID 24765068, 2014). "Since intracerebroventricular injection of CRH induces symptoms of depression in rodent, centrally released CRH may be implicated in depression etiology." (PMID 24318124, 2014). "Depression may cause an increase in the release of corticotropin-releasing hormone (CRH) from the placenta via the actions of catecholamines and cortisol." (PMID 17900360, 2007). "We hypothesize that receptor resistance of the CRH system can induce hypercortisolism: the CRH system is implicated in the response to depression and prolonged stress, and CRH SNPs are variants of depression risk." (PMID 38927393, 2024). "These opposite effects on CRH neurons may underlie sex difference in the prevalence of depression." (PMID 24318124, 2014). "Current studies have primarily focused on the 5-HT and NE pathways, but recent research indicates that glutamate, GABA, CRH, and oxytocin also play significant roles in the development of pain and depression." (PMID 39859152, 2025). "In a group of patients suffering from depression, increased levels of cortisol, CRH, and ACTH were observed." (PMID 40141110, 2025). "For the depression -like behaviors indicated by immobility time in the forced swim test, the results showed that CRH of HPA axis, GnRH of HPT and HPO axis (GnRH>CRH) dedicated to depression and respond to the treatment of QFY in male mice." (PMID 40438332, 2025).
depression (continued). "In the PVN, altering CRH signaling influences depressive-like behaviors in various models, including lipopolysaccharide (LPS)-induced depression, chronic social defeat stress (CSDS), and chronic unpredictable mild stress (CUMS) models." (PMID 40370500, 2025). "Elevated CRH, a critical HPA axis regulator, is associated with hyperactivity of this system in depression patients." (PMID 40900922, 2025). "Other hormones, including corticotropin-releasing hormone, adrenocorticotropin, and vasopressin, are elevated in depression, though findings are inconsistent." (PMID 40428308, 2025). "In fact, hypercortisolemic patients with depression, if stimulated with CRH, show a blunted ACTH response, indicating that, in these patient subgroups, the cortisol-mediated negative feedback on the corticotroph cells is possibly normal." (PMID 38092990, 2025). "Corticotropin-releasing hormone (CRH) containing neurons are a subtype of GABAergic neurons that play important roles in depression-like behaviors via the hypothalamic-pituitary-adrenal (HPA) axis." (PMID 40217549, 2024). "In chronically epileptic mice, activation of CRH neurons in the paraventricular nucleus (PVN) increases seizure susceptibility while inhibition is sufficient to decrease seizure susceptibility and depression-like behaviors." (PMID 40217549, 2024). "For instance, “Melancholic depression” or “Typical depression” was related to CRH neuronal hypoactive HPA axis, whereas “Atypical depression” was aligned with down-regulated HPA activity." (PMID 39363747, 2024). "It was found that the secretion and response of CORT, the level of CRH in cerebrospinal fluid and inflammation increased in patients with severe depression." (PMID 39539631, 2024). "When CSS was orally administered to CUMS rats continuously for 21 days, it was found that CRH levels increased and GR levels decreased in the hippocampus compared to the depression model group." (PMID 38628641, 2024). "In AD patients we observed a positive correlation between the Cornell depression score and PACAP-ir in the PVN, while in the same cohort we observed earlier a positive correlation between, the Cornell depression score and CRH in the PVN." (PMID 37226771, 2023). "On the other hand, atypical depression is characterized by hypoactive brain CRH activity and suppressed HPA axis." (PMID 37511494, 2023). "CRH is thought to be related to the development and progression of depression, accounting for many depression-related symptoms, such as insomnia, anxiety, psychomotor agitation, and decreased appetite." (PMID 36624454, 2023). "Earlier our group found, in the same patients, a positive correlation between the Cornell score for depression severity in dementia and the number of CRH-expressing neurons in the PVN." (PMID 37226771, 2023). "Hypercortisolism is common in patients with severe depression; it manifests in elevated levels of cortisol in the serum, cerebrospinal fluid (CSF), saliva and/or 24 h urine and elevated levels of corticotropin-releasing hormone (CRH) in the CSF." (PMID 37241007, 2023). "Melancholic depression was associated with hypersecretion of central CRH and a positive correlation was found between CRH level and the severity of depression." (PMID 37511494, 2023). "CRH and its receptors have fundamental neurobiological relationships with behavioural responses to stress in major depressive disorder." (PMID 36624454, 2023). "Increased activity of the HPA axis in patients with major depression is one of the well-known factors that increase the secretion of corticotropin-releasing hormone (CRH), leading to an increase in secretion of corticotropin and cortisol." (PMID 36864065, 2023). "For example, CRH is hypersecreted in depression, and insulin resistance is prevalent in depressive patients." (PMID 36430254, 2022).
depression (continued). "The relationship between PFNA and CRH was stronger among women who experienced stressful life events, depression, food insecurity, and financial strain compared to women who did not experience these stressors." (PMID 33824413, 2022). "Depression patients with hyperactive HPA axis are mainly characterized by elevated CRH, ACTH, CORT, and metabolite levels in the central and peripheral nervous system, especially in the hypothalamus." (PMID 36844911, 2022). "Although there is currently no consensus on a suitable biological biomarker(s) underpinnings depression, it has been reported that the cerebrospinal fluid of depressed patients contains elevated levels of CRH." (PMID 36552294, 2022). "The aim of our study was to investigate serum brain-derived neurotrophic factor (BDNF) and corticotropin releasing hormone (CRH) levels in vitiligo patients and healthy controls in relation to the observed symptoms of depression and anxiety disorders." (PMID 35508633, 2022). "In particular, excessive secretion of corticotropin releasing hormone (CRH) and corticosterone (CORT) can mediate neurodegeneration and induce cognitive impairment and loss of mood in patients with depression." (PMID 36204228, 2022). "Both centrally released CRH and increased levels of cortisol contribute to the signs and symptoms of depression." (PMID 36142325, 2022). "Recently, several studies have been conducted to ascertain the effects of CRH antagonists in animal models of depression." (PMID 36552294, 2022). "In depression, the corticotropin-releasing hormone (CRH) levels, and consequently the cortisol levels are elevated resulting in the inhibition of the action of gonadotropin-releasing hormone (GnRH) neurons, gonadotrophs, and gonads." (PMID 36387878, 2022). "Compared with the general population, the expression of CRH increases in patients with severe depression." (PMID 36059775, 2022). "The environmental stressor applied in this study was expected to increase the hypothalamic expression of CRH, with a consequent CRH-mediated role in FI depression exhibited by 95RB and MRB subjected to HS." (PMID 35002780, 2021). "Depression during pregnancy also increases the production of corticotrophin-releasing hormone(CRH) from the placenta, initiating premature labor, a scenario termed as the Placental Clock." (PMID 32555631, 2020). "Corticotropin-releasing hormone (CRH), which is elevated in depression patients, increases gastrointestinal permeability by recruiting mast cells." (PMID 32020020, 2020). "In major depression, the secretion of CRH is increased, and GC is overproduced, the sensitivity of GR is impaired, HPA negative feedback mechanism is damaged." (PMID 32281722, 2020). "Aging as well as some pathological conditions such as depression are accompanied by modifications in the CRH:GHRH ratio with an increase of CRH." (PMID 33391142, 2020). "Dysregulation of these neuropeptides is associated with depression, and reduced plasma levels of both NPY and CRH have been found in suicidal individuals." (PMID 31220174, 2019). "Evidence over the years for increased CRH activity initially led to the development of CRH receptor antagonists as putative treatments for depression." (PMID 30719038, 2019). "Accordingly, dysregulation of the CRH/CRHR1 system has been observed in stress-related psychopathologies including depression and anxiety disorders." (PMID 31619956, 2019). "In preclinical models central administration of CRH produces behavioral effects that closely resemble the symptoms of depression in humans." (PMID 30890970, 2019). "For example, it has been shown that people suffering from a stress-related disorder, such as major depression, have increased levels of CRH and decreased reproductive function." (PMID 30214395, 2018). "Stress increases the release of CRH and this CRH activates HPA axis in stress responses in PTSD patients with depression." (PMID 29302258, 2017).